KRAS (KRas proto-oncogene, GTPase)
Diseases named in the same sentence as KRAS in open-access papers (continued):
Sharing a sentence is not in itself a finding about the gene and the disease.
tumor (continued). "Twenty nine out of 85 tumor tissue samples (34%) were positive for one of the six KRAS mutations that we have tested." (PMID 25946211, 2015). "All in all, although the prominent role of hnRNPs in tumor progression has been already described, this is the first report showing a relation between KRAS mutational status and hnRNP acetylation." (PMID 26110767, 2015). "Similar mutations and KRAS gene amplification have been shown to confer secondary resistance to anti-EGFR treatment in the same tumor type." (PMID 25691052, 2015). "Because of intratumor heterogeneity, tumor cells containing mutated KRAS alleles frequently present as subclones in mCRC." (PMID 26701781, 2015). "Of the 121 tumours analysed, 48 (40%) had KRAS mutations, the mutations where located in codon 12 (65%), codon 13 (31%) and codon 61 (4%)." (PMID 25884297, 2015). "Oncogenic KRAS has a tumor-promoting role in conventional adenoma initiated by loss of APC, while oncogenic BRAF can initiate another type of CRC precursor, termed serrated adenoma, independently of APC." (PMID 26425654, 2015). "A Cox’s proportional hazards model was performed for multivariate analysis including age, stage, tumor differentiation, KRAS mutation status, and combined CIMP/MLH1 methylation status in relation to overall survival (OS)." (PMID 26121593, 2015). "The KRAS mutation was found in a tumor sample from a patient who was treated with neo-adjuvant chemotherapy." (PMID 26415226, 2015). "Higher frequency of KRAS mutations was observed in tumours from patients with higher disease stages; 28% in stage II; 38% in stage III and 62% in stage IV." (PMID 25884297, 2015). "Unusually, two patients with an EGFR mutation (one with the mutation in their primary tumour and one with the mutation in a lymph node metastasis) had an additional KRAS mutation in the corresponding metastases." (PMID 26338018, 2015). "The detection of KRAS mutations in cfDNA or circulating tumor cells has been reported to be clinically meaningful." (PMID 25954997, 2015). "Mutant KRAS was detected in 62% and 39%, respectively, of plasma DNA (n = 103, kappa statistics = 0.370, p < 0.05) and platelet RNA (n = 144, kappa statistics = 0.213, p < 0.05) of patients with a KRAS mutation in primary tumor tissue." (PMID 26525104, 2015). "All UICC stages were included in the sample set; with regard to molecular tumor characteristics, KRAS mutations were present in 27/76 (36%) while BRAF mutations were present in 9/76 (12%) of samples." (PMID 26106602, 2015). "The first study published reported that 38% of patients treated with the anti-EGFR monoclonal antibody cetuximab, who were known to have wt KRAS on the basis of tumor tissue analysis, later developed KRAS mutations." (PMID 25980577, 2015). "The high degree of intra-tumor heterogeneity has meant that it is important to develop sensitive and selective assays to detect low-abundance KRAS mutations in metastatic colorectal carcinoma (mCRC) patients." (PMID 26701781, 2015). "Five results showed a WT genotype for KRAS-tested mutations by cfDNA analysis, whereas tumor-tissue analysis showed a KRAS G13D mutation (n = 2), a KRAS G12D mutation (n = 2) or a KRAS G12V mutation (n = 1)." (PMID 25946211, 2015). "Toray has established a new 3D-Gene® assay for the detection of KRAS mutations in tumor tissues using the PCR-rSSO (PCR-reverse sequence-specific oligonucleotide) method." (PMID 25674493, 2015). "A female patient with an additional KRAS mutation and relapse after resection of her stage I tumor had repeatedly responded to therapy with pemetrexed." (PMID 25473901, 2015).
tumor (continued). "A high concentration of these ligands is supposed to be related with a more aggressive tumor growth, but the rates of KRAS mutations are lower in tumors overexpressing EGFR ligands." (PMID 26318427, 2015). "Analyses identified differences in the KRAS gene mutational status between HROC60 tumor and the corresponding cell line." (PMID 26618628, 2015). "In contrast, neither the SW48-G13D nor SW48-G12V xenograft model was sensitive to ixazomib (T/C = 1.05 and 0.99), suggesting that introduction of a KRAS mutation is sufficient to drive resistance to PI in tumor xenograft models in vivo." (PMID 26709701, 2015). "The presence of a KRAS mutation was also significantly associated with a tumour stage > I (p = 0.0240, FET)." (PMID 26506417, 2015). "On the other hand, the association between KRAS status and type of first-line chemotherapy can be explained by choice of treatment based on tumor histology, which is associated to the KRAS status." (PMID 26416458, 2015). "For example, Diaz and colleagues highlighted that 38% (9/24) of patients presenting with a tumor who were initially classified as wild-type KRAS developed detectable mutations in KRAS in serum analyzed during or after treatment." (PMID 26701781, 2015). "At the same time, it was demonstrated that the KRAS gene, both in its wild and mutated state, was capable of predicting both the response and its utility in the tumour against the use of EGFR inhibitors." (PMID 25932044, 2015). "Genomic analysis of tumor biopsies revealed the presence of KRAS mutation (G12D) and loss of CDKN2A/B." (PMID 26156229, 2015). "The RAS gene seems to be specific for tumours of the colon, pancreas, and lung, which have a high frequency of KRAS mutations." (PMID 25932044, 2015). "An additional study also demonstrated that cetuximab combined with first line chemotherapy is effective for patients with KRAS G13D tumor mutations." (PMID 25674493, 2015). "In our study, compared with WT carcinoma cases, both KRAS codon 12 and codon 13 mutations were associated with proximal (vs distal) tumor site of the colon." (PMID 25929517, 2015). "Two human tumor xenograft models with known KRAS and PIK3CA mutations (CUCRC40 and CUCRC98) were treated with alisertib and trametinib as single agents and in combination at various doses: alisertib 10 and 20 mg/kg and trametinib 0.5 and 1.5 mg/kg." (PMID 26136684, 2015). "The clinical diagnosis of metastatic CRC currently involves screening of tumor tissue for KRAS mutations so that patients with wild-type KRAS-containing tumors are only given anti-EGFR treatment." (PMID 25685149, 2015). "As established in previous studies, majority of tumor cell lines possess a mutation in either KRAS, NRAS or BRAF genes was sensitive to AZD6244 in vitro (IC50 < 1 μM)." (PMID 26567773, 2015). "We used CD3Z and CD8 expression in order to devise the mRNA-based Immune Score (mIS) and proceeded to partitioning analysis in 267 patients, with age, stage, tumour site (Right vs Left CRC), KRAS mutation and tumour mIS as input factors." (PMID 25970543, 2015). "There was one tumor demonstrating mutations in both KRAS and BRAF; this case was excluded from the analysis." (PMID 25929517, 2015). "Frequency of KRAS mutations and actionable mutations excluding KRAS by tumor type is demonstrated in this figure." (PMID 26015395, 2015). "KRAS mutational status was associated with tumor histology (P = 0.038) and smoking habit (P = 0.006)." (PMID 26416458, 2015).
tumor (continued). "The multiplexed SCODA mutation detection assay was used to analyze extracted DNA from patient tumor tissue and pre-operative plasma samples for the presence of mutations in KRAS, PIK3CA, BRAF and EGFR as defined in our panel." (PMID 25575824, 2015). "A multivariate model initially included gender, age at diagnosis, tumor size, tumor location, year of diagnosis, KRAS mutation, CIMP status and miR-21, miR-31, and miR-143 expression levels." (PMID 25797243, 2015). "The c.35G > A (p.Gly12Asp) KRAS mutation has extensively been reported in tumour tissue described in the open access database COSMIC (Catalogue Of Somatic Mutations In Cancer) suggesting its strong oncogenic character." (PMID 25928347, 2015). "In humans, the most frequent genetic alteration that underlies PDAC is an activating mutation of the KRAS oncogene, which occurs in >90% of tumours." (PMID 26438692, 2015). "Strong staining of KRAS (the KRAS mutation commonly had strong staining) in the tumor cell nuclei was significantly associated with FIGO stage (P = 0.011), tumor type (P = 0.025) and WHO grade (P = 0.027)." (PMID 26490766, 2015). "The concordance between primary tumor and CTCs was high (88.46%- 96.15%) and concerning KRAS and BRAF mutations comparable to previous studies." (PMID 25902072, 2015). "New mutations in RAS and PIK3CA emerged after therapy compared to archival tumour, and the emergence of multiple KRAS mutations in low levels after anti-EGFR therapy is a known resistance mechanism to anti-EGFR antibodies." (PMID 25889309, 2015). "The FDA recommends that CRC patient tumor biopsies be assessed for KRAS mutation status prior to treatment with anti-EGFR mAbs." (PMID 25823645, 2015). "It thus appears that tumor initiation and/or progression by KRAS or BRAF not only depends on mutational activation in the tumor-initiating cell, but also on successful evasion of common tumor suppressing mechanisms in the mutated clone." (PMID 26299805, 2015). "Specifically, 3 patients who demonstrated a KRAS wild-type in the primary tumor were found to have a mutated KRAS codon 12 allele in the CTC enriched cells fraction." (PMID 25902072, 2015). "Both mutations tend to be proximal tumor location and mucinous histology, but KRAS-mutated tumors are more common in female patients." (PMID 25929517, 2015). "Further to this, new targeted therapies are being developed for patients with other molecular aberrations; for example, selumetinib, cobimetinib and trametinib are being developed for patients with KRAS mutation-positive tumours." (PMID 26338018, 2015). "Analysis of a tumor biopsy revealed an activating KRAS mutation (G12D) and the patient was started on first-line treatment with Reolysin in combination with gemcitabine in March 2012." (PMID 26156229, 2015). "Approximately 40% of CRCs harbour mutations of KRAS that occur at early stages of the disease and are present throughout tumor progression to metastatic stages." (PMID 25568935, 2015). "Genome wide, this tumor had 3,889 somatic mutations including oncogenic mutation KRAS G13D and FGFR4 V550L." (PMID 25768946, 2015). "Tumours harbouring KRAS or EGFR mutations had always acquired these in the founding clone, whereas putative driver mutations in HGF were subclonal." (PMID 25555261, 2015). "Patients with tumours presenting both KRAS wild type and MSI had a reduced risk of dissemination (OR 0.22; 95% CI 0.08-0.62) and recurrence in disease stages II and III (OR 0.31; 95% CI 0.10-0.94) compared with all other groups." (PMID 25884297, 2015). "It is interesting to notice that several studies reported discordance in the KRAS mutational status between the primary tumor and the metastatic tissues." (PMID 25902072, 2015). "A patient with wt KRAS in the initial tumor tissue biopsy who had a transient response (4 months) to cetuximab-based therapy was then found to have a KRAS G13D mutation (0.88%) in cfDNA." (PMID 25980577, 2015).
tumor (continued). "KRAS gene isfrequently mutated in PanIN lesions, which are precursors of tumour cells, and theactivation of KRAS leads to enhanced proliferation and cell growth." (PMID 26603187, 2015). "When taken up by CRC cells with wt KRAS, EVs derived from CRC cells with mutated KRAS contained many tumour-promoting proteins, including KRAS and EGFR, and enhanced colony formation." (PMID 28936238, 2015). "When the analysis was focused on the type of KRAS, comparing the results of tumour response rate in participants who had the wild-type gene versus the mutated gene, the available results favoured wild-type KRAS." (PMID 26557880, 2015). "The initially reported PFS and OS (median 7.6 months and 12.8 months respectively) were considerably higher than historical results in chemotherapy refractory CRC patients with KRAS mutated tumours and chemotherapy refractory CRC patients in general." (PMID 26386973, 2015). "Consistently, clinical studies revealed that human cancer patients with BRAF- or KRAS-mutated tumours have the worst therapy prognosis." (PMID 26168967, 2015). "In non–small cell lung carcinoma, IL-8 is overexpressed under the influence of KRAS and enhances the stromal response by inducing inflammation and angiogenesis, which are associated with tumor proliferation and negatively correlate with patients’ survival." (PMID 26674732, 2015). "Since oncogenic mutations of KRAS have been frequently described in RMS tumor samples, we employed constitutively activated Kras (KrasG12D) in our mosaic model." (PMID 25992772, 2015). "Among the 302 tumours examined for gene mutations, KRAS mutations were found in 40.7% and BRAF mutations in 4.9%." (PMID 25970543, 2015). "We have recently shown in a prospective study that NSCLC patients with mutated KRAS tumor had a worse response to first-line platinum-based treatment compared to KRAS(wt) patients and unpublished results." (PMID 26353932, 2015). "KRAS is the most frequently mutated isoform in tumours and this has been proposed to be due to DNA sequence-specific susceptibility to mutation or specific spatio-temporal expression patterns versus the other isoforms." (PMID 26560143, 2015). "A total of 211 patients had both tumour and plasma samples available for the reliable detection of KRAS mutations." (PMID 25875772, 2015). "Let-7 is a family of tumor suppressor microRNAs that are frequently suppressed in solid tumors, where KRAS mutations are highly prevalent." (PMID 25946136, 2015). "It has been shown that patients with tumor mutations in KRAS exon 2 as well as KRAS exons 3 or 4 or NRAS exon 2, 3, or 4 are likely to show resistance to anti-EGFR agents." (PMID 26452027, 2015). "This initial KRAS SNP has since been found and validated as a marker of risk in multiple tumor types, including colorectal, head and neck squamous cell carcinoma, endometrial cancer, breast and ovarian cancer and others." (PMID 26226002, 2015). "From 2008–2013, the European indication for panitumumab required that patients’ tumor KRAS exon 2 mutation status was known prior to starting treatment." (PMID 26491871, 2015). "Multivariate logistic regression model associations between patient, tumor and KRAS or BRAFV600E mutation status." (PMID 26042813, 2015). "Mathematical modeling of such resistance suggested that subclones harboring the KRAS mutations were present in low frequency in the tumor before treatment." (PMID 26474549, 2015).
tumor (continued). "miRNA expression levels and KRAS-variant genotype were correlated with patient and tumor characteristics, and survival outcomes were evaluated by variant allele type." (PMID 24732316, 2014). "All 3 tumor samples had KRAS mutations, while 2 tumors contained mutations in the APC gene and the PIK3CA gene." (PMID 24943349, 2014). "The higher frequency of KRAS mutations in tumor tissue was also evident when different KRAS mutation subgroups were considered." (PMID 25491325, 2014). "Whereas initiation of PDAC tumorigenesis has been found to be driven by oncogenic KRAS mutations, disease progression has been associated with frequent loss of tumor suppressors within tumor cells, such as the PI3K/PTEN pathway." (PMID 24624093, 2014). "The association of the KRAS-variant with prognosis across tumor types has also been widely reported." (PMID 24732316, 2014). "This is in line with reports about metabolic remodeling driven by tumor cells and KRAS mutations, supporting the feasibility and robustness of our explorative untargeted LC-MS strategy." (PMID 24952473, 2014). "In the light of recent findings on the role of some molecular markers in the pathogenesis and progression of this tumor, we have also carried out molecular analyses to verify the methylation of p16 promoter and mutational status of KRAS, PIK3CA and EGFR." (PMID 25358264, 2014). "Patient characteristics in the high vs. low pPI3K signaling CRC cohorts were well balanced in terms of their tumor stage, chemotherapy treatments, and mutational status of the oncogenes KRAS and BRAF." (PMID 25090459, 2014). "High expression of Ki-67 has previously been described to correlate with more advanced tumour stage and peritoneal spread, whereas KRAS mutation reportedly is associated with well-differentiated EOC tumours." (PMID 24568264, 2014). "The tumor was found to have a KRAS hotspot mutation (chr12:25,398,285C > G, G12R) at a similar allelic fraction in the primary (SBT, 57%) and recurrent (LGSC, 44%) sample by both Ion Torrent and MiSeq." (PMID 25523272, 2014). "A high WHR was significantly associated with an increased risk of KRAS-mutated CRC (ptrend = 0.046) as compared to KRAS wild type tumours in women, with a significant heterogeneity in the highest tertile (p = 0.032)." (PMID 24918610, 2014). "In patients with a KRAS mutated tumor, the RAS pathway is permanently activated, leading to constant cell signalling and proliferation independent of the EGFR." (PMID 25375154, 2014). "In total, 12 of the 15 homogeneous cases harbored wild-type KRAS and two cases exhibited the same mutation in each tumor." (PMID 24765171, 2014). "For the analysis of the prognostic impact of KRAS mutation status, we used data from patients for which DNA from both tumor tissue and plasma were available (n = 242)." (PMID 25491325, 2014). "Analysis of the KRAS mutation revealed that the same mutation was present in the primary tumor and the corresponding liver metastasis in 94 cases (87.2%; 95% confidence interval [CI] 93.6–98.2%)." (PMID 24668895, 2014). "It is highly recommended that all patients with mCRC who are candidates for anti-EGFR monoclonal antibody therapy have their tumours tested for KRAS mutation." (PMID 25361007, 2014). "Single living tumor cells were efficiently isolated from these spiked tumor cells by a micromanipulator, and KRAS mutation, HER2 gene amplification and overexpression, for example, were successfully detected from such isolated single tumor cells." (PMID 24523941, 2014). "Dramatic tumor shrinkage was noted in a recent mutated KRAS lung cancer model when treated with a combination of a dual PI3K/mTOR inhibitor and a MEK (MAP/ERK kinase) inhibitor." (PMID 24624093, 2014).